TMED10 (transmembrane p24 trafficking protein 10)
Description:
Cargo receptor involved in protein vesicular trafficking and quality control in the endoplasmic reticulum (ER) and Golgi. The p24 protein family is a group of transmembrane proteins that bind coat protein complex I/COPI and coat protein complex II/COPII involved in vesicular trafficking between the membranes. Acts at the lumenal side for incorporation of secretory cargo molecules into transport vesicles and involved in vesicle coat formation at the cytoplasmic side. Mainly functions in the early secretory pathway and cycles between the ER, ER-Golgi intermediate compartment (ERGIC) and Golgi, mediating cargo transport through COPI and COPII-coated vesicles. In COPII vesicle-mediated anterograde transport, involved in the transport of GPI-anchored proteins by acting together with TMED2 as their cargo receptor; the function specifically implies SEC24C and SEC24D of the COPII vesicle coat and lipid raft-like microdomains of the ER. Recognizes GPI anchors structural remodeled in the ER by the GPI inositol-deacylase/PGAP1 and the metallophosphoesterase MPPE1/PGAP5 (By similarity). In COPI vesicle-mediated retrograde transport, involved in the biogenesis of COPI vesicles and vesicle coat recruitment. Involved in trafficking of amyloid beta A4 protein and soluble APP-beta release (independent from the modulation of gamma-secretase activity). Involved in the KDELR2-mediated retrograde transport of the toxin A subunit (CTX-A-K63)together with COPI and the COOH terminus of KDELR2 (By similarity). On Golgi membranes, acts as a primary receptor for ARF1-GDP, a GTP-binding protein involved in COPI-vesicle formation. Increases coatomer-dependent GTPase-activating activity of ARFGAP2 which mediates the hydrolysis of ARF1-bound GTP and therefore modulates protein trafficking from the Golgi apparatus. Involved in the exocytic trafficking of G protein-coupled receptors F2LR1/PAR2 (trypsin and tryspin-like enzyme receptor), OPRM1 (opioid receptor) and P2RY4 (UTD and UDP receptor) from the Golgi to the plasma membrane, thus contributing to receptor resensitization. In addition to its cargo receptor activity, may also act as a protein channel after oligomerization, facilitating the post-translational entry of leaderless cytoplasmic cargo into the ERGIC. Involved in the translocation into ERGIC, the vesicle entry and the secretion of leaderless cargos (lacking the secretion signal sequence), including the mature form of interleukin 1/IL-1 family members, the alpha-crystallin B chain HSPB5, the carbohydrate-binding proteins galectin-1/LGALS1 and galectin-3/LGALS3, the microtubule-associated protein Tau/MAPT, and the annexin A1/ANXA1; the translocation process is dependent on cargo protein unfolding and enhanced by chaperones HSP90AB1 and HSP90B1/GRP9. Could also associates with the presenilin-dependent gamma-secretase complex in order to regulate gamma-cleavages of the amyloid beta A4 protein to yield amyloid-beta 40/Abeta40.
Synonyms: p24delta1; TMP21; P24(DELTA); p24d1; p23; S31I125; S31III125; Tmp-21-I
Tractability: Antibody: UniProt places it where antibodies can reach, with medium confidence; UniProt predicts a signal peptide or a membrane-spanning region; its Gene Ontology location is reachable by antibodies, with medium confidence. PROTAC: ubiquitination databases record sites on it; its protein half-life has been measured.
Gene: Protein-coding gene on chromosome 14 (75,131,443 to 75,176,652, reverse strand). Ensembl gene ENSG00000170348.
Subcellular location: Endoplasmic reticulum membrane; Endoplasmic reticulum-Golgi intermediate compartment membrane; Golgi apparatus membrane; Golgi apparatus, cis-Golgi network membrane; Golgi apparatus, trans-Golgi network membrane; Cytoplasmic vesicle, secretory vesicle membrane; Cell membrane; Melanosome
Subcellular location (Human Protein Atlas): Golgi apparatus
Pathways (Reactome):
Vesicle-mediated transport: COPI-dependent Golgi-to-ER retrograde traffic; COPI-mediated anterograde transport; COPII-mediated vesicle transport; Cargo concentration in the ER
Gene Ontology:
Molecular function: protein binding; protein transmembrane transporter activity; syntaxin binding
Biological process: COPI-coated vesicle budding; cytosol to ERGIC protein transport; intracellular protein transport; positive regulation of interleukin-1 production; positive regulation of protein secretion; protein localization to ERGIC; regulation of amyloid-beta formation; COPI coating of Golgi vesicle; COPII vesicle coating; endoplasmic reticulum to Golgi vesicle-mediated transport; Golgi organization; Golgi vesicle transport; regulated exocytosis; retrograde vesicle-mediated transport, Golgi to endoplasmic reticulum; vesicle cargo loading; protein transmembrane transport
Cellular component: endoplasmic reticulum; endoplasmic reticulum membrane; endoplasmic reticulum-Golgi intermediate compartment; endoplasmic reticulum-Golgi intermediate compartment membrane; gamma-secretase complex; Golgi apparatus; Golgi membrane; melanosome; cis-Golgi network; COPI-coated vesicle; ER to Golgi transport vesicle membrane; membrane; plasma membrane; secretory granule membrane; trans-Golgi network transport vesicle; transport vesicle; zymogen granule membrane; transport vesicle membrane
Genetic constraint (gnomAD): Loss-of-function variants: 7 observed, 22.8 expected, observed/expected ratio (o/e) 0.31, 90% interval 0.17 to 0.58. The upper end of that interval is the gene's LOEUF score, 0.58, which puts it in group 2 of 6, group 1 being the genes least tolerant of losing a copy. Missense variants: 161 observed, 289.39 expected, observed/expected ratio (o/e) 0.56, 90% interval 0.49 to 0.63. Synonymous variants: 113 observed, 114.49 expected, observed/expected ratio (o/e) 0.99, 90% interval 0.85 to 1.15.
Homologues: Orthologues: chimpanzee TMED10 (99% identical), macaque TMED10 (98% identical), dog TMED10 (95% identical), pig TMED10 (95% identical), guinea pig TMED10 (93% identical), mouse Tmed10 (93% identical), rat Tmed10 (89% identical), zebrafish tmed10 (78% identical), tropical clawed frog tmed10l (67% identical), Caenorhabditis elegans tmed-10 (53% identical), Drosophila melanogaster bai (53% identical). Paralogues in human: TMED4 (34% identical), TMED9 (34% identical), TMED2 (21% identical), TMED7 (18% identical), TMED1 (18% identical), TMED3 (18% identical), TMED5 (17% identical), TMED6 (16% identical).
Diseases named in the same sentence as TMED10 in open-access papers:
TMED10 is named in the same sentence as 26 diseases in open-access papers, as found by Europe PMC text mining. Sharing a sentence is not in itself a finding about the gene and the disease. The quoted sentences say what the papers report.
Alzheimer disease (9 papers, 2018 to 2023). A progressive, neurodegenerative disease characterized by loss of function and death of nerve cells in several areas of the brain leading to loss of cognitive function such as memory and language. "A single nucleotide polymorphism in TMED10 that resulted in heightened TMP21 expression was found to be genetically associated with Alzheimer’s disease in patients." (PMID 36733337, 2022). "More broadly, TMED2 and TMED10 are also linked to disorders and diseases including Alzheimer’s disease (AD), kidney disorders, and diabetes." (PMID 32293333, 2020). "TMED10 negatively regulates autophagy, and the expression of TMED10 is reduced in Alzheimer’s disease patients." (PMID 37931110, 2023). "TMED9 and TMED10 may thus be crucial in halting the progression of Alzheimer's disease." (PMID 37928880, 2023).
diabetes mellitus (3 papers, 2020 to 2025). A metabolic disorder characterized by abnormally high blood sugar levels due to diminished production of insulin or insulin resistance/desensitization. "Notably, two of them, Meg3 and Tmed10, have been linked to exocrine pancreatic differentiation in prior studies, especially in the context of diabetes mellitus." (PMID 41331466, 2025).
prostate carcinoma (3 papers, 2023 to 2025). A carcinoma that arises from epithelial cells of the prostate gland. "This may be explained by TMED10's role as a biomarker of favorable prognosis in prostate cancer and BCL11B's function as a tumor suppressor." (PMID 41472855, 2025).
lung carcinoma (2 papers, 2022 to 2025). "Mechanistically, TMED10 may exert tumor-promoting effects via disruption of TGF-β receptor complex formation, as observed in lung cancer models, where it attenuates Smad2 activation and downstream TGF-β signaling pathways." (PMID 40826138, 2025).
melanoma (2 papers, 2024 to 2025). A malignant, usually aggressive tumor composed of atypical, neoplastic melanocytes. "To functionally validate this enhanced activation signature of Tmed10-deficient T cells, we performed a co-culture of OT-I/Cas9 T cells with murine melanoma B16F10-OVA cells." (PMID 39510795, 2024). "While prior studies have implicated SNRPA1 and LSM4 in RNA splicing and cancer, and TMED10 in autophagy and vesicle trafficking in melanoma and liver cancer, their involvement in OC has been explored systematically by a limited number of studies." (PMID 40826138, 2025).
xerostomia (2 papers, 2020 to 2023). Dryness of the mouth resulting from reduced salivary secretion. "In SS patients both with xerostomia (sicca) and without xerostomia (non-sicca), TMED10, PDIA4, CANX, APP, and TMBIM6 expression was lower than in HS." (PMID 33066537, 2020).
colon cancer (1 paper, 2014). "Consistent with non-redundant functions in animals, we have only identified TMED3 even though we have detected all TMED mRNAs except that for TMED10 in the human colon cancer cells used (data not shown)." (PMID 24920608, 2014).
colorectal cancer (1 paper, 2024). A primary or metastatic malignant neoplasm that affects the colon or rectum. "Additionally, a positive correlation was identified between TMED1 and other members of the TMED family (TMED2, TMED4, TMED9, and TMED10) in colorectal cancer." (PMID 38392302, 2024).
oral squamous cell carcinoma (1 paper, 2020). "They used a similar proteomics approach and reported TMED10 among the 13 unique proteins in oral squamous cell carcinoma." (PMID 31945087, 2020).
viral infection (1 paper, 2024). "Interestingly, according to Gene Ontology, TMED10 and KTN1 are not directly related to immune responses, but their products interact with SARS-CoV-2 proteins, suggesting a role in the viral infection." (PMID 38637586, 2024).
tumor (10 papers, 2007 to 2025). "PTEN is secreted by tumor cells via binding to TMED10 and then binds to PLXDC2 on tumor associated macrophages (TAMs) and induces inflammatory status through triggering JAK2-STAT signaling, thus contributing to the tumor suppressor function of PTEN." (PMID 40766638, 2025). "The analysis of the whole tumor digest confirmed the observed relatively low abundance of Tmed10 KO CD8 T cells from the tumor microenvironment (TME)." (PMID 39510795, 2024). "Furthermore, our analysis showed that the correlation between TMED10 and the microbiome gradually weakened from A to early and advanced tumor stages, while the correlation between BCL11B and the microbiome progressively increased." (PMID 41472855, 2025). "Importantly, the Tmed10 KO cells that were able to successfully reside in the tumor were generally fitter, as evidenced by their reduced expression of an exhaustion signature." (PMID 39510795, 2024). "However, and importantly, when we quantified the number of CD8 T cells present in the spleen and tumor, we observed much fewer Tmed10 KO T cells had infiltrated into tumors than WT T cells." (PMID 39510795, 2024). "mAb 12G12 suppressed tumor in a TMED10 dependent and through NFκB-AKT pathway." (PMID 37670977, 2023). "The genes most positively associated with TMBIM6 expression, including LAMP2, APLP2, TMED10, PPAPDC2, ZNF652, and CTSB, are primarily involved in lysosomal and ER trafficking, membrane dynamics, and metabolic resilience—pathways that facilitate tumor survival under cellular stress conditions." (PMID 41516091, 2025). "TMED10 inhibits the TGF-β-induced migration of lung cancer cells, thus serving as a tumor suppressor." (PMID 35805075, 2022). "TMED10, interrupting TGF-β receptor complex formation, reduces the breast cancer xenograft tumor growth through negatively modulating TGF-β-induced pro-oncogenic signaling." (PMID 35805075, 2022). "The strong positive correlation of SNRPA1, TMED10, and PROM2 with suppressive immune regulators like IDO1 and VTCN1, and negative correlation with Th1 and MAIT cell infiltration, suggest that these genes may contribute to an immune-evasive tumor microenvironment." (PMID 40826138, 2025). "For instance, SNRPA1 and TMED10 expression showed consistent negative correlations with Th1 cells and MAIT cells indicating that their overexpression may hinder immune cell recruitment or function within the tumor microenvironment." (PMID 40826138, 2025).
cancer (4 papers, 2016 to 2025). A tumor composed of atypical neoplastic, often pleomorphic cells that invade other tissues. "Analysis of pull-down products by mass spectrometry (MS) revealed that the DEspR-protein interacts with several proteins involved in intracellular trafficking, angiogenesis, and/or cancer: vimentin, Gal-3, Gal-1 and TMED10." (PMID 27301377, 2016). "Besides, it has been confirmed that isolated small peptides derived from the extracellular domain of TMED10 could treat cancers with abnormal TGF-β signaling activity by antagonizing TGF-β signaling." (PMID 35754792, 2022). "Quantitatively, TMED10 and PROM2 silencing reduced proliferation to approximately 55–60% of the control levels (***P < 0.001), indicating a strong inhibitory effect on cancer cell growth." (PMID 40826138, 2025).
infection (2 papers, 2015 to 2020). The state of being infected such as from the introduction of a foreign agent such as serum, vaccine, antigenic substance or organism. "Further assessment of cells subjected to KD conditions and low MOI infection revealed cells with KD VCP or TMED10 displayed defective cell proliferation and altered cell morphology." (PMID 32910773, 2020).
TMED10 also shares sentences with these, for which no sentence is quoted: breast carcinoma (2 papers); malaria (2); neurodegenerative disease (2); Ataxia (1); endocrine disorders (1); glioma (1); HCMV infection (1); Hepatic steatosis (1); Insulin resistance (1); kidney disorder (1); liver cancer (1); non-alcoholic fatty liver disease (1); schizophrenia (1).